HMGB1 (high mobility group box 1)
Diseases named in the same sentence as HMGB1 in open-access papers (continued):
Sharing a sentence is not in itself a finding about the gene and the disease.
tumor (continued). "The effect of HMGB1 on tumor cells are broad as revealed by transcriptomic analysis, which offers mechanistic clues for future studies." (PMID 32382012, 2020). "Passively released by necrotic cells or actively produced by activated monocytes, macrophages, and tumor cells, HMGB1 enters to the extracellular space and exerts there its proinflammatory activities." (PMID 32684831, 2020). "To sum up, we can draw a conclusion that the expression of fibulin-3 and HMGB1 can well distinguish tumor tissue from adjacent tissue." (PMID 33230247, 2020). "Most studies have revealed that HMGB1 is an inducer for tumor cell autophagy and promotes tumor cell survival through autophagy." (PMID 32551121, 2020). "In the present study, we demonstrated that Arf1 inhibition resulted in lipid droplet accumulation, mitochondrial defects, ER stress, induction of DAMPs (Calr, ATP, HMGB1), and anti-tumor immune responses." (PMID 31924786, 2020). "In the present work, we analyzed the expression of HMGB1 redox isoforms in different inflammatory conditions in skeletal muscle, from acute injury to muscle wasting, in tumor microenvironment, in spleen, and in liver after drug intoxication." (PMID 32670275, 2020). "In the previous experiment, we found that HIF-1α was also upregulated in tumor tissues synchronized with HMGB1." (PMID 32328193, 2020). "The combined induction of antitumor immunity by TIM-3 and HMGB1 has become a potential target for tumor immunogenic chemotherapy and development." (PMID 32660524, 2020). "One study showed that tumor-induced overexpression of high-mobility group box 1 (HMBG1) induces a Treg phenotype." (PMID 32102342, 2020). "These DAMPs are characterized by adenosine triphosphate (ATP), calreticulin (CRT), heat shock protein 70/90 (HSP70/90) and group box-1 protein (HMGB-1), which are secreted or exposed on the extracellular membrane surface of the dying tumor cells." (PMID 32899183, 2020). "In vivo, the ability of HMGB1 to promote tumor development is seriously diminished as MDSCs are exhausted viaanti-Gr-1 antibodies." (PMID 32551121, 2020). "In summary, in the present study, we demonstrated that HMGB1 secreted by hypoxic tumor cells induces CD62Ldim neutrophils, thereby promoting lung metastasis via enhanced NETs formation." (PMID 32943604, 2020). "In a tumor vaccination mouse model, using HMGB1‐depleted tumor cells or neutralizing HMGB1 by specific antibodies compromised the ability of mice to resist tumorigenesis." (PMID 33179413, 2020). "Under a high glucose state, HMGB1 expression is elevated and released from cell nuclei into the cytoplasm and extracellular matrix of tumor." (PMID 33117687, 2020). "Since extracellular HMGB1 can act as a proinflammatory cytokine, we tested blood serum HMGB1 in healthy and tumor-bearing mice after the CAP treatment." (PMID 32698492, 2020). "Specifically, the tumor cell apoptosis from Eu-FBCP/PTX treatment triggered the expression of HMGB1 and CRT, demonstrating greater DC maturation and activation of antitumor IFN-γ+CD8+ and granzyme B+CD8+ T cells compared with Eu-s/PTX." (PMID 34138119, 2020). "Notwithstanding the immunosuppressive effects of sustained, inflammation-related oxidative stress, the following subsections describe additional mechanisms of HMGB1-mediated immunosuppression driving tumor progression." (PMID 32664328, 2020). "The same group observed release of the RAGE ligand, high mobility group protein 1 (HMGB1), during several tumor cell death types." (PMID 32344698, 2020). "As for the phenomenological model, tumor cells can be converted into dying tumor cells when treated by chemotherapeutic agents, whereas dendritic cells become active after sensing ATP, HMGB1, CALR, and/or ANXA1." (PMID 33281620, 2020). "Sustained HMGB1 signaling limits chemotherapeutic responses in tumor cells, promoting resistance via enhanced autophagy, inhibiting both intrinsic and extrinsic-mediated apoptotic pathways in cancer cells." (PMID 33013860, 2020).
tumor (continued). "The following sections of the review are focused on putative mechanisms that underpin the involvement of HMGB1 in tumor promotion, progression and invasion/metastasis." (PMID 32664328, 2020). "Tumor antigens from dying cells can activate antitumor adaptive immune response, where HMGB1 plays a critical role." (PMID 32698492, 2020). "The authors also suggest that HMGB1 released by the tumor helps to recruit glutamine from the muscle to supply cancer cells as an energy source." (PMID 33604297, 2020). "We established a tumor microenvironment of BC cells in vitro and found that hypoxia exposure promoted BC cell migration and activated HMGB1/HIF‐1α signaling pathway." (PMID 32436353, 2020). "Taken together, these data suggest that HMGB1 secreted by the primary tumor plays an important role in lung pre-metastatic niche formation." (PMID 32943604, 2020). "Our study established PTX as a bona fide ICD-inducing agent as validated by measuring the levels of CRT, ERp57, ATP, and HMGB1 in several mouse and human tumor cell lines." (PMID 32724476, 2020). "Apart from the direct killing of tumor cells by IRE, the apoptosis of tumor cells is accompanied with the expression or release of DAMPs, including HMGB1, calreticulin, and HSP70, illustrating that IRE can also induce ICD of tumor cells." (PMID 32508058, 2020). "ICD is a mechanism of induced cell death in which tumor cells expose calreticulin on their surface and release ATP or HMGB1 during apoptosis or necrosis." (PMID 33321934, 2020). "While restricted to the nucleus in normal condition, HMGB1 is freed in the tumor microenvironment upon ICD, thereby constituting another “alarm” signal for the immune system." (PMID 33281620, 2020). "HMGB1 released from dying tumor cells stimulates TLR-2, 4 or 9 signaling in DCs leading to antitumor effects." (PMID 31293597, 2019). "Our results show that while nsPEF treatments induced HMGB1 release in both tumor cell lines, extracellular ATP was detected only in CT26-treated cells." (PMID 31861079, 2019). "HMGB1 is also expressed in the cell surface in mononuclear immune cells, neuronal cells, and tumor cells." (PMID 31731454, 2019). "As one most common DAMPs, HMGB1 is complicated in tumor treatment resistant by its paradoxical dual activities." (PMID 31558702, 2019). "ICD is characterized by release of a series of immunostimulatory damage-associated molecular patterns (DAMPs) such as high mobility group box 1 (HMGB1) protein, extracellular ATP, cytoplasmic calreticulin, and endogenous nucleic acids by the dying tumor cells." (PMID 31324798, 2019). "In a mouse xenograft model, the treatment of cisplatin with Morin hydrate reversed the increased expression of PARP and HMGB1 and significantly suppressed tumor growth." (PMID 31311167, 2019). "The results indicated that tumor size, lymph node metastasis and clinical stage were significantly correlated with high HMGB1 expression." (PMID 31331356, 2019). "The subsequent release of ATP and high-mobility group box 1 (HMGB1) by tumor cells undergoing ICD promotes DC activation and triggers antigen-specific T cell responses." (PMID 31781498, 2019). "At the same time, various alarmins such as heat shock proteins (HSPs) and high mobility group box-1 protein (HMGB1) increase in the irradiated tumor bed." (PMID 31058025, 2019). "While HMGB1, as a DAMP, can attract immune cells to the tumor site and engage receptors such as TLRs, culminating in immune activation, its presence in human tumor tissues and circulation is frequently associated with disease severity and progression." (PMID 31379812, 2019). "On the other hand, as a tumor-promoting agent, tumor cell-released HMGB1 enhanced immunosuppressive cell recruitment, tumor angiogenesis, invasion and metastasis." (PMID 30744691, 2019).
tumor (continued). "NK cells can respond to different types of chemokines released in tumor sites and can release chemotactic high mobility group box 1 (HMGB1) capable of amplifying the antitumor response by attracting additional NK cells at the tumor site." (PMID 31623224, 2019). "In WT mice, β-lap treatment increased the number of tumor-reactive T cells and this effect was abolished when co-administrated with anti-HMGB1 neutralizing Ab." (PMID 31324798, 2019). "In our previous study, cryo-thermal therapy caused extensive tumor necrosis and elevated extracellular release of DAMPs (damage associated molecular patterns), such as HSP70, CRT and HMGB1 (unpublished data) from necrotic tumor cells." (PMID 31519961, 2019). "In fact, the involvement of HMGB1 in cancer is complicated, and nuclear/intracellular and extracellular forms of HMGB1 have been demonstrated to participate in tumor development, progression, invasion, metastasis, and response to chemotherapeutics." (PMID 30891101, 2019). "The expression of Ki-67 proliferation antigen was dramatically weaker in tumor tissues with sh-HMGB1 cells and stronger in xenografts with HMGB1 overexpression as seen by IHC staining." (PMID 31410208, 2019). "Extracellular calreticulin (CRT) and release of HMGB1 are two important DAMPs required for the induction of immunogenic cell death, responsible for inducing an effective anti-tumor immune response." (PMID 32642649, 2019). "Analysis of tumor cells indicated that DOC strongly induced HMGB1 expression in a dose-dependent manner." (PMID 30744691, 2019). "EP inhibits hepatic, gastric, gallbladder, and prostate tumor growth in vivo and in vitro by inhibiting HMGB1 and downregulating the HMGB1-RAGE pathway." (PMID 30891101, 2019). "Phosphatidylinositol 3-kinase/Akt (PI3K/AKT) pathway, which is promoting proliferation of tumor cells by regulating cell cycle 1 and is closely related to the invasion and metastasis of tumor, also reported to be mediated by HMGB1." (PMID 30962261, 2019). "It remains to be determined how the modulation of the tumor immune microenvironment by radiation-induced HMGB1 is ultimately dictating the response to radiation." (PMID 31015520, 2019). "A study on glioblastoma multiforme cell lines (GL261) in xenotransplant models showed that the infection of tumor cells with NDV leads to the elevated level of cell surface calreticulin as well as the increased secretion of HMGB1 and PMEL17 tumor antigens." (PMID 31217023, 2019). "For example, in ECs autophagy contributes to the secretion of high mobility group box 1 (HMGB1), which is highly upregulated in the tumor endothelium." (PMID 30692642, 2019). "Analysis of the tumours revealed an increased intensity in nuclear staining for HMGB1 in combination‐treated tumours, with some scattered areas of increased intensity of nuclear HMGB1 staining in the HU‐only‐treated tumours." (PMID 31044505, 2019). "HMGB1-induced autophagy not only promotes tumor growth by directly enhancing tumor cell survival, but also by boosting the immunosuppressive nature of the TME by perpetuating regulatory cells." (PMID 31379812, 2019). "In a mouse model, the inhibition of the HMGB1-RAGE interaction can inhibit tumor growth and metastasis by decreasing the activation of p44/p42, p38 and SAP/JNK MAP kinases, which can lead to the expression of matrix metalloproteinase enzymes (MMPs)." (PMID 31247032, 2019). "It has been reported that HSPs are released from dying and necrotic tumor cells by irradiation followed by the late release of HMGB1." (PMID 31058025, 2019). "We then examined the anti-tumor immune responses developed in the tumors in order to determine how the immune balance within the tumor immune microenvironment is affected by radiation and HMGB1 inhibition." (PMID 31015520, 2019).
tumor (continued). "High mobility group box 1 (HMGB1) expression is upregulated in ESCC lesions as compared to adjacent normal mucosa and also is associated with tumor recurrence after postoperative radiotherapy (PORT) in ESCC patients." (PMID 31683722, 2019). "Tumor-derived exosomes containing HMGB1 can modulate the microenvironment through subversion of the immune response." (PMID 31379812, 2019). "We observed protein expression of autophagy marker LC3 was positively correlated with HMGB1 in ESCC tumor tissues (r = 0.642, P < 0.0001)." (PMID 30755598, 2019). "To further address the essential role of HMGB1, we evaluated the tumor-specific T cell response when blocking signaling in conjunction with β-lap treatment." (PMID 31324798, 2019). "Known ligands to TIM-3 are Galectin-9, Ceacam1, HMGB1 (High Mobility Group Box 1) and phosphatidylserine, all expressed by a variety of cells including tumor cells." (PMID 31060337, 2019). "An HMGB1-TSLP (thymic stromal lymphopoietin) axis has been demonstrated, where tumor-derived HMGB1 and TSLP enhance DC-mediated activation of Tregs, a phenomenon that was dependent on the presence of the TSLP receptor on DCs." (PMID 31379812, 2019). "Cell-associated danger signals associated with ICD like calreticulin promote phagocytosis, while adjuvants such as HMGB1 or F-actin induce DC activation, tumor Ag processing and cross-presentation." (PMID 30961656, 2019). "We found alarmin HMGB1 in the sonicated tumor lysate from Colon 26 cells both in the supernatant and the precipitate after centrifugation at 20,000 x g for 15 minute." (PMID 31058025, 2019). "Another key event dictating the immunostimulatory activity of ICD is the release of the High mobility group box 1 (HMGB1) protein that is essential for an efficient cross-presentation of tumor-derived antigens by DC." (PMID 31191545, 2019). "Using two established patient derived xenograft (PDX) models (HPCx1 and HPCx2), we explored the role of HMGB1 in mediating the tumor relapse." (PMID 31558702, 2019). "Further studies are needed to validate our findings in an orthotopic model and to investigate the role of biomarkers such as serum levels of HMGB1 and tumor infiltrating immune cells as predictive markers for treatment outcomes." (PMID 31015520, 2019). "Both calreticulin and HMGB1 were found to be essential for the antigen-specific T-cell responses in murine tumor models." (PMID 30941308, 2019). "In comparison, tumors grew even slower with both IR treatment and HMGB1 depletion in term of tumor weight (P < 0.01) and tumor volume (P < 0.01), indicating the additional suppressive effect brought by HMGB1 depletion." (PMID 30755598, 2019). "Taken together, we demonstrate that the combination of radiation and HMGB1 inhibition results in attenuation of pro-tumor immune mechanisms within the tumor immune microenvironment by decreasing the frequency of immunosuppressive cells." (PMID 31015520, 2019). "Based on previous studies, the intracellular protein HMGB1 is known to be secreted from tumor cells following chemotherapy or radiotherapy, and it is also known that HMGB1 can bind to TLR4 on DCs and activate downstream signaling pathways." (PMID 30819254, 2019). "In order to confirm the molecular mechanisms of HMGB1 inducing cancer cell dedifferentiation in vivo, we firstly determined the tumor initiation potential of CD133− cancer cells in similar in vitro conditions." (PMID 31558702, 2019). "Anthracyclines induce ICD, resulting in exposure of calreticulin on the surface of tumor cells, tumor secretion of high mobility group box 1 and activation of NLR Family Pyrin Domain Containing 3 (NLRP3) inflammasome in DC." (PMID 30979057, 2019). "As a member of the DAMP family of proteins we anticipated a role for radiation-induced HMGB1 in stimulating either pro-tumor or anti-tumor immune response within the tumor microenvironment." (PMID 31015520, 2019).
tumor (continued). "HMGB1 (high mobility group B1) protein, one of the DAMPs, is released from damaged, inflamed, and tumor cells which in turn promotes tumor cell survival." (PMID 30988279, 2019). "As an endogenous factor, HMGB1, derived from dying tumor cells post chemo- or radiation-therapy, has been shown to induce cytokine secretion, migration, and maturation of dendritic cells to initiate antigen-specific adaptive immune responses." (PMID 30744691, 2019). "Patients with gastric cancer have high plasma and tumor tissue HMGB1 expression and this correlates with poor prognosis." (PMID 31379812, 2019). "Our results show that HSP70 and HMGB1 over-expressed by tumor cells are released into tumor beds upon irradiation, and trap intravenously-administered eMIP." (PMID 31058025, 2019). "The CM@M‐MSN@Ce6+Laser+ACMF treatment significantly increased HMGB1 release in orthotopic 4T1 tumor tissues, which is a result that is consistent with our in vitro findings." (PMID 31763151, 2019). "HMGB1 supplementation in the culture medium promoted tumor cell growth in T98G cells, and this effect was canceled by papaverine." (PMID 31100066, 2019). "In head and neck cancer patients, HMGB1 acts as a chemokine for Tregs and enhances their suppressive capacity, with both tumor-infiltrating and circulating Tregs expressing the HMGB1 receptors TLR4 and RAGE." (PMID 31379812, 2019). "One of the known early signals that occur following radiotherapy is the passive release of the alarmin protein High mobility group box-1 (HMGB1) from tumor cells." (PMID 31015520, 2019). "We also found that high mobility group box 1 (HMGB1), released by irradiated necrotic tumor cells, participated in tumor repopulation." (PMID 31706322, 2019). "HMGB1 treatment promoted tumor regrowth and increased TLR2-YAP-HIF-1α signaling activation compared with the parental control." (PMID 31558702, 2019). "Libraries constructed from the PCa cell line, PC-3, and from patients’ PCa primary tumor have been screened by the yeast 2-hybrid approach (Y2H) using HMGB1 and HMGB2 baits." (PMID 31694235, 2019). "Damage-associated molecular patterns (DAMPs) or alarmins such as HSP70 and HMGB1 released by tumor cells following irradiation work synergistically with eMIP to recruit and activate killer T cells." (PMID 31717914, 2019). "On the other hand, tumor-derived HMGB1 has been shown to enhance the immunosuppressive capacity of Tregs11,12 and promote the recruitment, proliferation, and immune inhibitory functions of MDSCs13,28,29 and TAMs30,31." (PMID 31015520, 2019). "In HCC, the high mobility group box-1 protein (HMGB1)-YAP-dependent aerobic glycolysis played an important role in tumor growth." (PMID 31142342, 2019). "Intracellular translocation of HMGB1 facilitates its interaction with mtDNA in the cytosol where together they activate TLR9 signaling pathways to enhance tumor growth." (PMID 30695997, 2019). "We also observed other damage-associated molecular patterns (DAMPs32) such as heat-shock protein 70 (HSP70) and high-mobility-group-protein B1 (HMGB1) to be increased on the tumor cell surface with oxidizing treatment." (PMID 30679720, 2019). "According to these studies, 5-fluoruracil (5-FU) increased tumor immunity in a mouse model by renal cell xenograft through an increase of CTL infiltration mediated by the High Mobility Group Box 1 (HMGB1)." (PMID 30991686, 2019). "miR-27a low-expressing tumor cells released more HMGB1 into the extracellular space, displaying a more autophagic phenotype able to induce DCs phenotypical and functional maturation in vitro." (PMID 31379812, 2019). "HMGB1 knockdown cells exhibited significantly smaller tumor volume and weight than control cells 25 days after injection." (PMID 31410208, 2019). "The HMGB1 (High Mobility Group Box 1) gene plays a role in several cellular processes, including inflammation, cell differentiation and tumor cell migration." (PMID 30616509, 2019).